YAP1 (Yes1 associated transcriptional regulator)
Diseases named in the same sentence as YAP1 in open-access papers (continued):
Sharing a sentence is not in itself a finding about the gene and the disease.
cyst (8 papers, 2019 to 2024). A sac-like closed membranous structure that may be empty or contain fluid or amorphous material. "Surprisingly, we noted that PC2 derepression was associated with reduced 3D cyst growth, restored MitoTracker signal, and downregulation of pCreb1, Yap1, Mettl3, and c-Myc expression in Pkd1RC/-; Pkd2∆17/∆17 cells compared to Pkd1RC/- cells." (PMID 35965273, 2022). "Further studies revealed that loss of YAP1/WWTR1 reduced cyst formation in a Pkd1-deficient mouse model." (PMID 34545930, 2021). "In particular, the pathway's effectors Yap1 and Taz have been associated with cyst formation." (PMID 31038742, 2019). "When treated with RGLS4326, cells exhibit reduced proliferation, smaller cyst sizes, and a decreased expression of key proteins involved in disease progression, including Yap1 and c-Myc." (PMID 39595570, 2024). "We also stained the cystic lesions with CDX2, CK18, and YAP-1, markers of trophectoderm, and we found that all of those markers were expressed in the cyst wall." (PMID 38892233, 2024). "Consistently, we observed that compared to Pkd1RC/-; Pkd2+/+ kidneys, Pkd1RC/-; Pkd2∆17/∆17 kidneys exhibited reduced c-Myc and Yap1 expression and lower cyst proliferation and interstitial inflammation." (PMID 35965273, 2022). "We further validated that ectopic YAP1 expression attenuated peripheral Ki67+ cell proliferation in xenografted tumors despite unexpected larger cyst-like growth in YAP1-overexpressing xenografts compared to those formed by vector control cells." (PMID 35930163, 2022). "As an upstream scaffold protein, kidney-specific deletion of Sav1 in mice induced hyperproliferation of renal tubular epithelial cells and cyst formation through activating YAP1." (PMID 34545930, 2021). "Also, Scrib was found to regulate renal cyst formation through Yap1, and either knockdown or overexpression of Yap1 induced cyst formation in zebrafish." (PMID 34545930, 2021). "The low cyst formation of BAP‐EB derived from hEPSC‐em with an intact exon 1 and a deleted exon 4 of YAP1 supported the importance of the TEAD‐binding domain in TE development." (PMID 36775869, 2023).
multiple myeloma (8 papers, 2017 to 2025). "This provides the rational for the development of YAP1 activators for patients with myeloma harboring low YAP1 levels." (PMID 31139207, 2019). "Although nuclear ABL1 triggers cell death via interaction with YAP1 in normal cells, low YAP1 levels in myeloma – due to genetic inactivation or reduced expression – prevent nuclear ABL1-induced apoptosis (left)." (PMID 31139207, 2019). "The significance of the Hippo-YAP1 signaling pathway has recently been identified in myeloma cells." (PMID 30835743, 2019). "This may be relevant for myeloma treatment, because YAP1 is under control of the serine-threonine kinase, STK4, and pharmacological inactivation of STK4 may restore YAP1 levels and, thereby, kill myeloma cells (right)." (PMID 31139207, 2019). "Hence, the role of YAP1 in multiple myeloma progression especially EM needs to be further studied." (PMID 35059315, 2021). "To further analyze the intratumoral heterogeneity in terms of YAP1/MYC expression, we collected the single-cell transcriptome data of 477 myeloma cells from GSE106218 which contained 9 MM samples and 3 paired EM samples." (PMID 35059315, 2021). "The activity of DNA repair, glycolysis, and oxidative phosphorylation was significantly higher in YAP1-MYC+ MM, which is in concordance with EM myeloma cells based on single-cell analysis." (PMID 35059315, 2021). "The prognostic significances of YAP1/MYC were further confirmed in 4 external independent datasets including GEO datasets (GSE9782 and GSE2658), TCGA dataset (MMRF-COMPASS), and Oncomine dataset (Zhan myeloma 2) in over 2,000 MM patients." (PMID 35059315, 2021).
polycystic ovary syndrome (8 papers, 2017 to 2024). A disorder that manifests as multiple cysts on the ovaries. "A recent genome-wide association study (GWAS) of polycystic ovary syndrome (PCOS) in European cohorts has identified six susceptibility loci mapping to 11q22.1 (YAP1), 2p21 (THADA), 11p14.1 (FSHB), 2q34 (ERBB4), 12q21.2 (KRR1), and 5q31.1 (RAD50)." (PMID 28195137, 2017). "Polycystic ovary morphology is also associated with some of these signals, specifically with YAP1." (PMID 38408933, 2024). "In addition, aberrant Hippo signaling and genetic variants of YAP1 have been correlated with enhanced susceptibility for polycystic ovary syndrome (PCOS), characterized by enlarged ovaries, while gene copy variations for BIRC1 have been reported in women with POI." (PMID 37171807, 2023). "Furthermore, methylation of the YAP1 promoter in polycystic ovary syndrome (PCOS) was also shown to increase YAP1 protein levels." (PMID 31216773, 2019).
subependymoma (8 papers, 2017 to 2024). Subependymoma is a rare and slow growing type of ependymoma, often presenting in middle-aged adults, found more commonly in men than in women, usually located in the fourth and lateral ventricles and manifesting with variable symptoms including headache, nausea, and loss of balance. "It has been proposed that ST-EPNs may be divided into three molecular subgroups; ST-EPN-RELA (RELA fusion-positive), ST-EPN-YAP1 (YAP1 fusion-positive) and ST-SE (subependymoma)." (PMID 30514397, 2018). "Three subgroups have been identified among supratentorial tumors (ST-EPN): subependymomas; EPN, YAP1 fusion-positive; and EPN, ZFTA fusion-positive (as specified by the World Health Organization’s classification)." (PMID 38581034, 2024). "Supratentorial (ST) EPNs can be further classified into subependymoma (ST-SE) and two subgroups characterized by fusion genes, including, C11orf95-RELA (ST-EPN-RELA) or YAP1-MAMLD1 (ST-EPN-YAP1)." (PMID 29383182, 2017). "None of these were diagnosed as subependymoma following central review, where only a single case of YAP1 fusion was identified by FISH (EP117)." (PMID 30514397, 2018). "Supratentorial tumors are subdivided into subependymoma (ST-SE) and two subgroups characterized by fusions: ST-EPN-RELA, characterized by expression of C11orf95-RELA fusion transcript and by exceptionally poor prognosis, and ST-EPN-YAP1, characterized by YAP1 fusions." (PMID 30279357, 2018).
benign prostatic hyperplasia (7 papers, 2020 to 2025). A non-cancerous nodular enlargement of the prostate gland. "Mechanistically, GPER stimulation enhances yes-associated protein 1 (YAP1) phosphorylation and degradation, thereby suppressing prostatic hyperplasia." (PMID 40837016, 2025). "Targeting YAP1 may represent a promising approach to break the vicious cycle and alleviate inflammation‐associated benign prostatic hyperplasia (BPH) progression." (PMID 38050650, 2024). "The fibrotic microenvironment strengthens mechanical cue, which, in turn, induced cytoskeleton remodeling and YAP1 reactivation, thereby forming a positive feedback loop to promote prostatic hyperplasia and fibrosis." (PMID 38050650, 2024).
colon adenocarcinoma (7 papers, 2017 to 2025). "(C) Spearman correlation of the expression levels of YAP1/TAZ/TEAD target genes with SUNO1 in colon adenocarcinoma patient tumor samples." (PMID 33108271, 2020). "In Kaiser colon database analysis, comparing normal colon tissues and colon adenocarcinoma, we found that YAP1 mRNA was approximately 2.2-fold higher in the adenocarcinoma samples." (PMID 28241877, 2017). "Moreover, USP2-AS1 overexpression decreased the p-LATS1, LATS1, LATS2, and p-YAP1 levels and increased total YAP1 level in colon adenocarcinoma cell lines." (PMID 38226210, 2024). "Importantly, Verteporfin, a YAP1 inhibitor which disrupts YAP-TEAD interactions, led to a significant suppression of the colonic adenocarcinomas." (PMID 36210463, 2022). "Our analysis uncovered a positive correlation between USP52 and YAP1 as well as its targeted genes CCN1 (CYR61) and CCN2 (CTGF) in the TCGA-Colon Adenocarcinoma (COAD) cohort." (PMID 40962058, 2025).
endometriosis (7 papers, 2020 to 2025). The growth of functional endometrial tissue in anatomic sites outside the uterine body. "The hippo/yes-associated protein 1 (YAP1) signaling pathway plays an important role in endometriosis." (PMID 40130159, 2025). "Furthermore, miR-21-5p and Hippo/yes-associated protein 1 (YAP1) signaling pathway were upregulated, while the expression of PR was downregulated in endometriosis." (PMID 37834449, 2023). "Both YAP1 mRNA and protein are elevated in endometrial stem cells derived from women with endometriosis, consistent with pathological function." (PMID 40378301, 2025). "Treatments with verteporfin (VP) and dienogest have been shown to downregulate miR-21-5p and YAP1 expression, leading to upregulation of PR expression, thus improving progesterone resistance in endometriosis in humans and mouse models." (PMID 37834449, 2023). "In conclusion, our findings suggested that circATRNL1 promoted the EMT in endometriosis by upregulating YAP1 through sponging miR-141-3p and miR-200a-3p." (PMID 32728069, 2020). "Based on these data, we confirmed that circATRNL1 acted as a ceRNA to modulate endometriosis progression via the miR-141-3p/miR-200a-3p/YAP1 axis." (PMID 32728069, 2020). "More importantly, IL-8 receptor inhibitor, reparixin, and YAP1 inhibitor, veterporfin, inhibit angiogenesis and the growth of endometriotic lesion in the animal model of endometriosis." (PMID 32389123, 2020). "The same study also reported that inhibition of YAP1 by its inhibitor, verteporfin, not only decreases E2 and PGE2 production but also causes the regression of endometriotic lesion in the mouse model of endometriosis." (PMID 32389123, 2020). "Our findings demonstrate that abnormal upregulation of circATRNL1 regulates cell proliferation and motility and promotes EMT process via the miR-141-3p/miR-200a-3p–YAP1 axis in vitro, which could contribute to the progression of endometriosis." (PMID 32728069, 2020). "Finally, rescue assays demonstrated that circATRNL1 improved the EMT by modulating miR-141-3p/miR-200a-3p/YAP1 in endometriosis." (PMID 32728069, 2020). "Overall, these results suggested that YAP1 may promote EMT progression in endometriosis." (PMID 32728069, 2020). "In addition, the YAP1/TEAD1 complex increased proliferation and decreased autophagy of endometrial stromal cells derived from women with endometriosis." (PMID 40378301, 2025). "Interestingly, transcriptional analysis of uteri lacking Yap1 and Wwtr1 uncovered pathway annotations connected to endometriosis." (PMID 40378301, 2025). "Up-regulation of YAP1/miR-21-5p decreases PGR expression and plays a negative role in the development of endometriosis." (PMID 39057685, 2024).
gastric tumors (7 papers, 2019 to 2024). "Although genomic tumor profiling provides information of Hippo pathway activation, the present study demonstrates that inhibition of Yap1 activity has anti-tumor effects in gastric tumors driven by oncogenic mutations and inflammatory cytokines." (PMID 37957015, 2024). "To identify transcriptional changes associated with Yap1 gene ablation, we isolated EpCAM+ epithelial cells from gastric tumors obtained from 20 wk-old Gp130FF; Yap1WT and Gp130FF; Yap1KO mice for bulk RNASeq analysis." (PMID 37957015, 2024). "Surprisingly, we also observed an increase in macrophages in Yap1-deficient gastric tumors." (PMID 37957015, 2024). "Single-cell RNA-Seq analysis of murine gastric tumors demonstrated varied expression patterns of the Hippo pathway transcriptional complex members, namely, Yap1, Taz, and Tead1, in gastric tumor cells." (PMID 37957015, 2024). "We first explored the function of Yap1 in well-established gastric tumors and administered tamoxifen to 16 wk-old when 100% of treatment naïve Gp130FF mice exhibited large gastric lesions." (PMID 37957015, 2024). "This suggests that Yap1 as a key driver of early events in inflammation-driven gastric tumor development in the Gp130FF mice." (PMID 37957015, 2024). "Conditional, Tff1:CreERT transgene-mediated Yap1 gene knockout in the gastric epithelium of Gp130FF mice reduced gastric tumor incidence." (PMID 37957015, 2024). "To assess the effects of Yap1 on gastric tumor initiation, we also administered tamoxifen to Gp130FF; Tff1:CreERT2; Yap1fl/fl mice at 9 wk of age." (PMID 37957015, 2024). "To identify Yap1-expressing cells, we used single-cell RNA-sequencing (scRNA-seq) to profile cells of gastric tissue from WT control mice and gastric tumors derived from Gp130FF mice." (PMID 37957015, 2024). "When we used scRNA-seq to profile the Gp130FF gastric tumor lesions, Yap1 expression was localised specialised, gastric parietal cells, foveolar cells, and in the tumor epithelial cells." (PMID 37957015, 2024). "Interestingly, increased Yap1 levels were observed in developing and neoplastic gastric tumors when compared with normal gastric tissue." (PMID 37957015, 2024). "Up-regulation of YAP1, IL11, IL6, and STAT3 mRNA transcript expression was observed in human gastric tumor samples when compared with normal gastric tissue." (PMID 37957015, 2024). "As with the gastric tumor subtypes, expression of TEAD1, but not that of YAP1 or STAT3, varied across the TME subtypes." (PMID 37957015, 2024).
idiopathic pulmonary fibrosis (7 papers, 2020 to 2025). Idiopathic pulmonary fibrosis (IPF) is a nonneoplastic pulmonary disease that is characterized by the formation of scar tissue within the lungs in the absence of any known cause. "The lncPFAR promotes lung fibroblast activation and ECM deposition by competitively binding miR-138 to regulate the YAP1–Twist axis, leading to the development of idiopathic pulmonary fibrosis (IPF)." (PMID 40221424, 2025). "In idiopathic pulmonary fibrosis (IPF), lncRNA PFAR regulated YAP1-Twist axis through targeting miR-138 as ceRNA, affected fibrogenesis in fibrotic lung." (PMID 31924195, 2020).
intrahepatic cholangiocarcinoma (7 papers, 2020 to 2026). A carcinoma that arises from the intrahepatic bile duct epithelium in any site of the intrahepatic biliary tree. "HIPPO/YAP1 signalling is also implicated in Ang II-mediated proliferation in intrahepatic cholangiocarcinoma (iCCA), with ARBs disrupting AGTR1+ cancer-associated fibroblast (CAF) MFAP5/Notch1 signalling by impeding YAP/TEAD nuclear translocation and reducing tumour proliferation." (PMID 41408463, 2026). "In intrahepatic cholangiocarcinoma (iHCC), losartan reduced stromal density by inhibiting YAP1/LAT1 dephosphorylation and MFAP5-mediated Notch1 signalling from AT1R+ CAFs." (PMID 41408463, 2026). "Some studies also reported the mutual-indispensable and direct binding of YAP1 and β-catenin in intrahepatic cholangiocarcinoma." (PMID 40604818, 2025). "For instance, circACTN4 functions as a sponge to eliminate miR-424-5p to upregulate and recruit Yes-associated protein 1 (YAP1), which exerts a positive effect on inducing Frizzled-7 (FZD7) and in turn facilitates the development of intrahepatic cholangiocarcinoma." (PMID 36875073, 2023). "However, the role and mechanism of YAP1 in intrahepatic cholangiocarcinoma remains unclear." (PMID 33552968, 2020).
myocardial infarction (7 papers, 2019 to 2025). Gross necrosis of the myocardium, as a result of interruption of the blood supply to the area, as in coronary thrombosis. "The hypertrophic response was observed in animal models of pressure overload and myocardial infarction in the presence of endogenous YAP1." (PMID 41213910, 2025). "After simulated IR injury using a hypoxic chamber, AC 16 cells overexpressing YAP1 showed a reduction in apoptosis, hypertrophy, and generation of ROS, hinting to the potentiality of YAP1 as a therapeutic target after myocardial infarction." (PMID 32887493, 2020). "The increasing evidence for a role of the Hippo pathway in cardiac regeneration in small animal models led us to investigate YAP1 in a sheep model of myocardial infarction and repair." (PMID 31167392, 2019). "This novel path may be worth pursuing as a potential pretreatment and therapy for myocardial infarction patients on Earth, as high levels of YAP1 protect cells during differentiation and aid in improving cardiac function." (PMID 31167392, 2019).
nasopharyngeal carcinoma (7 papers, 2020 to 2025). A carcinoma arising from the nasopharyngeal epithelium. "Cytoplasmic leukemia inhibitory factor promotes vascular dissemination and local invasion of nasopharyngeal carcinoma by modulating the YAP1–focal adhesion kinase (FAK)/paxillin signaling pathway." (PMID 40066231, 2025). "Regarding nasopharyngeal carcinoma (NPC), the Epstein–Barr virus can promote fibrosis and NPC progression by activating signaling of YAP1/fibroblast activation protein (FAP) α in fibroblasts." (PMID 38176714, 2024). "High intracellular LIF is correlated with lower metastasis-free and recurrence-free survival in nasopharyngeal carcinoma, in which xenograft zebrafish and mouse models reveal that LIF enhances vascular invasion, invadopodia formation, and focal adhesion kinases via suppression of YAP1." (PMID 35204717, 2022).
osteoarthritis (7 papers, 2020 to 2025). A noninflammatory degenerative joint disease occurring chiefly in older persons, characterized by degeneration of the articular cartilage, hypertrophy of bone at the margins and changes in the synovial membrane. "YAP1 has been shown to play an important role in chondrocyte development, fracture repair and osteoarthritis, and YAP1 is involved in the regulation of inflammatory factors." (PMID 37217512, 2023). "While the mechanistic role of Yap1 in regulating cartilage dysfunction has been explored, our osteoarthritic synovial organoid study could confirm a poorly understood role of Yap1 in osteoarthritis synovia." (PMID 40583463, 2025). "Recently, several studies have described the role of YAP1 in osteoarthritis (OA)." (PMID 33178690, 2020).
pulmonary hypertension (7 papers, 2019 to 2024). Increased pressure within the pulmonary circulation due to lung or heart disorder. "Moreover, verteporfin, an inhibitor of YAP1, reduces the S1P-induced proliferation of pulmonary arterial smooth muscle cells and hypoxia-induced pulmonary arterial hypertension, indicating that YAP1 is associated with the development of SphK1-induced pulmonary hypertension." (PMID 38255229, 2024). "YAP1 has been studied in pulmonary hypertension; it is suggested that YAP/TAZ activation may play a role in initiating pulmonary vascular ECM remodelling by activating pulmonary adventitial fibroblast proliferation in response to increased pulsatility and shear stress." (PMID 39495769, 2024). "YAP1 promoted AF proliferation and impaired AF apoptosis in pulmonary arteries, controlled ECM remodelling, consequently initiated pulmonary hypertension." (PMID 39495769, 2024).